ARL14EPL (ARF like GTPase 14 effector protein like)
Tractability: No criterion of Open Targets' tractability assessment is met for any kind of drug.
Gene: Protein-coding gene on chromosome 5 (116,032,324 to 116,060,118, forward strand). Ensembl gene ENSG00000268223.
Genetic constraint (gnomAD): Loss-of-function variants: 15 observed, 16.47 expected, observed/expected ratio (o/e) 0.91, 90% interval 0.61 to 1.4. The upper end of that interval is the gene's LOEUF score, 1.4, which puts it in group 5 of 6, group 1 being the genes least tolerant of losing a copy. Missense variants: 210 observed, 188.38 expected, observed/expected ratio (o/e) 1.11, 90% interval 1 to 1.25. Synonymous variants: 78 observed, 66.52 expected, observed/expected ratio (o/e) 1.17, 90% interval 0.98 to 1.42.
Homologues: Orthologues: chimpanzee ARL14EPL (100% identical), macaque ARL14EPL (95% identical), pig ARL14EPL (90% identical), rat Arl14epl (89% identical), mouse Arl14epl (88% identical), guinea pig ARL14EPL (87% identical), dog ARL14EPL (86% identical), tropical clawed frog ARL14EPL (62% identical), zebrafish zgc:153292 (12% identical), zebrafish zgc:163143 (11% identical), Drosophila melanogaster CG13894 (5% identical). Paralogues in human: ARL14EP (33% identical), THAP1 (12% identical), THAP3 (11% identical), THAP7 (10% identical), THAP2 (9% identical), THAP8 (5% identical), THAP6 (3% identical).